FGFR1 (fibroblast growth factor receptor 1)
Diseases named in the same sentence as FGFR1 in open-access papers (continued):
Sharing a sentence is not in itself a finding about the gene and the disease.
breast cancer (continued). "In HR (+)/HER2 (‐) breast cancers, increased expression of FGFR1 was found in hormone‐resistant breast cancer and in patients who received CDK4/6 inhibitors, and these patients can receive 19% of the objective response rate (ORR) treated by lucitanib." (PMID 33655556, 2021). "We found that TIC/EMT-enriched breast cancers were elevated in gene signatures associated with both MET and FGFR1 signalling pathway activation." (PMID 33772015, 2021). "According to GSEA results, SHH pathway genes were significantly upregulated in FGFR1 patients in both discovery cohorts of breast cancer." (PMID 34722544, 2021). "Fibroblast Growth Factor Receptor 1 DNA amplification is the most frequently reported FGF-pathway alteration in breast cancer." (PMID 34722544, 2021). "Anecdotal studies have reported on FGFR1 overexpression in breast cancer cohorts, but a standardized test for diagnosing overexpression has been lacking so far." (PMID 33579347, 2021). "The data suggest that FGFR1 overexpression-induced upregulation of ER-mediated transcription is a critical factor contributing to palbociclib resistance in FGFR1-overexpressing breast cancer cells." (PMID 34831231, 2021). "We show that up to 25% of HR+ breast cancer cases harbor amplification and/or overexpression of FGFR1." (PMID 33579347, 2021). "PD173074, a potent FGFR1 inhibitor, exhibits apparent antitumor activity in basal-like breast cancer cell lines that express autocrine FGF2." (PMID 34839358, 2021). "In this work, we studied in the incidence and prognostic role of amplification and overexpression of FGFR1 in a cohort of Lum-A and Lum-B HR+ breast cancer patients." (PMID 33579347, 2021). "Previously, FGFR1 was shown to promote stemness in malignant subpopulations in lung cancer and breast cancer." (PMID 33456711, 2021). "Turner and co-workers have shown that stimulation with FGF2 led to the development of resistance to tamoxifen in breast cancer cells with elevated expression of FGFR1." (PMID 34830951, 2021). "In the current study, we used luminal A breast cancer cell line models to demonstrate FGFR1-induced palbociclib resistance with mechanistic insight." (PMID 34831231, 2021). "In a preclinical model of breast cancer using an ER+ cell line (MCF-7), the overexpression of FGFR1 causes a resistance to treatment with fulvestrant and a CDK4/6 inhibitor, either palbociclib or ribociclib." (PMID 33535617, 2021). "Nuclear FGFR2 was recently found to negatively regulate hypoxia-induced cell invasion in prostate cancer and nuclear FGFR1 was positively corelated with pancreatic and breast cancer progression." (PMID 34830836, 2021). "FGFR1 amplification (8p12) is one of the most common focal amplifications in breast cancer (around 10%), especially for the ER-positive phenotype." (PMID 34203389, 2021). "Of note, IFL2 is located at the 8p chromosome, where other genes with a particular oncogenic role in breast cancer, such as FGFR1, has been described as amplified." (PMID 34439272, 2021). "We also found that our deep-learning classifier predicted well (AUC > 0.65) on the CNA status in breast cancer, including six genes of FGFR1, EIF4EBP1, KAT6A, HEY1, ZNF217, and RAB25." (PMID 34556802, 2021). "Our correlation analysis revealed that EGFR expression was strongly correlated with expressions of mTOR (r= 0.262–0.496) and FGFR1 (r= 0.203–0.348) in liver, lung, kidney, glioblastoma, colon, head and neck, and breast cancers." (PMID 33842373, 2021). "For that purpose, a comprehensive and integrated strategy was devised to establish the clinical relevance of FGFR1 modulation in breast cancer." (PMID 34722544, 2021). "In breast cancer specifically, molecular alternations in FGFR1 and FGFR2 receptors are the most common reported." (PMID 33191899, 2021). "In lung and breast cancer cell lines resistant to ErbB inhibitors, the increased expression of FGFR1 and/or FGF2 accompanied EMT." (PMID 34830951, 2021).
breast cancer (continued). "We next sought to establish if TICs derived from human breast cancers were specifically dependent on FGFR1 and MET signalling." (PMID 33772015, 2021). "In this study, we demonstrate that FGFR1 overexpression significantly attenuated the palbociclib-induced inhibition of CSC stemness of breast cancer cells, as indicated by the anchorage-independent growth and tumorsphere assays that detect CSC self-renewal." (PMID 34831231, 2021). "Treatment of patients with ER+/FGFR1-amplified breast cancers with letrozole, an aromatase inhibitor, increased the expression of FGFR1 and FGFs, as well as the nuclear localization of FGFR1 and ERα." (PMID 34830951, 2021). "To verify the findings from the MCF-7 cell line model, we examined the effect of FGFR1 overexpression on palbociclib response using another luminal A breast cancer cell line, T47D." (PMID 34831231, 2021). "Most importantly, in a patient-derived xenograft model with FGFR1-amplified ER+ breast cancer, the addition of the selective FGFR TKI erdafitinib to palbociclib and fulvestrant led to a complete tumor regression in some of the animals." (PMID 33535617, 2021). "In a study involving 1875 breast cancer patients, amplification of the FGFR1 gene was observed in 10.5% of patients." (PMID 33535617, 2021). "Initially, in TCGA dataset of 1,098 patients, clinical relevance of FGFR1 expression with breast cancer patients was assessed." (PMID 34722544, 2021). "Activation of FGFR1 induces hyaluronan (HA) synthesis via STAT3 pathway and causes accumulation of HA in extracellular matrix (ECM) of breast cancer cells." (PMID 34830951, 2021). "Since SHH pathway dysregulation is reported as an early event in several breast cancer studies, we selected SHH pathway to evaluate the association of FGFR1 and SHH pathway in modulating breast carcinogenesis." (PMID 34722544, 2021). "Previous studies have shown that FGFR1 amplification was common in breast cancer patients with early relapses and poor clinical outcomes." (PMID 33710807, 2021). "FGFR1 inhibition is known to promote infiltration of myeloid-derived suppressor cells (MDSCs), that exhibit strong immunosuppressive activity, into the breast cancer TME and promote both cancer progression and metastasis." (PMID 34540690, 2021). "Earlier, reduced FGFR1 was reported in multiple cancers including lung, pancreas, and breast cancers." (PMID 34061869, 2021). "FGFR1 amplification is an independent biomarker of a poor prognosis in patients with ER (+) breast cancer." (PMID 33655556, 2021). "FGFR1 is a proven transcriptional target of FOXC1 in breast cancer, following its own transcriptional upregulation by TGFβ pathway activation." (PMID 34540690, 2021). "In this context, amplified FGFR1 signaling has been included among the mechanisms involved in acquired resistance to lapatinib+trastuzumab co-targeted therapies in HER2-enriched breast cancers." (PMID 33081025, 2020). "In particular, breast cancer patients with the FGFR1 amplification frequently harbor activating alterations in the PIK3CA gene." (PMID 33081025, 2020). "N-cadherin stabilizes FGFR1 and decreases its internalization, thus promoting invasion in breast cancer cells, and N-Cadherin/FGFR crosstalk promotes neurite outgrowth." (PMID 33352931, 2020). "A trend of an increasing number of driver alterations of breast cancer-related genes was observed in recurrence samples as compared to primary tumors, including alterations in FGFR1, ESR1, NF1, BRCA1, and PTEN genes." (PMID 33059724, 2020). "BGJ398, a highly potent and selective pan-FGFR kinase inhibitor in clinical trials, has demonstrated antitumor activity in advanced cholangiocarcinoma patients with FGFR2 alterations and promoted tumor reductions in FGFR1-amplified breast cancer patients." (PMID 31987043, 2020). "Our results have a bioinformatics-based component and an in vitro-based component to gain insight into the interplay between FGFR1, leptin, and adiposity in breast cancer." (PMID 33019728, 2020).
breast cancer (continued). "In particular, amplification of FGFR1 located at 8p11-12, resulting in overexpression, occurs in less than 10% across all breast cancer subtypes, in approximately 10–16% of luminal-type breast cancers, and 4% in triple-negative breast cancer." (PMID 32517171, 2020). "The mean age of the patients with FGFR1-amplified breast cancer was 60 years, and they had a mean BMI of 27 kg/m2." (PMID 32852708, 2020). "Similar observations have been reported for FGFR1 amplification within breast cancer and other types of carcinoma." (PMID 32058674, 2020). "Of the 29 types of primary cancer, the average FGFR1 mRNA expression in breast cancer is the sixth highest overall (2.8852), and third highest among cancers where a significant relationship between leptin mRNA and FGFR1 mRNA was observed." (PMID 33019728, 2020). "It is known that FGFR1 can promote tumor progression and invasion in various cancers including gastric cancer, prostate cancer, and breast cancer." (PMID 32380883, 2020). "Another promising biomarker in breast cancer is the fibroblast growth factor receptor 1 gene (FGFR1, chromosomal region: 8p11.2-p12)." (PMID 32852708, 2020). "We present a scenario for a patient who has estrogen receptor (ER)–positive breast cancer with FGFR1 amplification." (PMID 31990579, 2020). "In particular, the FGFR1 locus (8q12) has been found to be amplified in nearly 15% of hormone receptor (HR)-positive breast cancer and in approximately 5% of the aggressive triple-negative breast cancer (TNBC)." (PMID 33081025, 2020). "Accumulating evidence suggests that FGF signaling induced by FGFR1/2 amplification attenuates the response to PI3K blockage in PIK3CA-mutant breast cancer." (PMID 32907621, 2020). "Most breast cancer patients with FGFR1 amplification showed moderate differentiation (G2, 69.7%) and a luminal subtype with positive hormone receptor status and predominantly HER2- negative status (ER+, 90.9%; PR+, 78.8%; HER2+, 9.1%)." (PMID 32852708, 2020). "Following the analysis of FGFR1 mRNA and leptin mRNA in primary breast cancer, we analyzed the relationship of FGFR1 mRNA and leptin mRNA in normal breast tissue, breast tumor-adjacent tissue, and tissue from metastatic breast cancer." (PMID 33019728, 2020). "In another study, FGFR1-amplified tumors had increased expression of genes integral to cell cycle progression in ER+ endocrine-resistant breast cancer, and suggest that FGFR1 amplification promotes cancer cell growth and endocrine resistance." (PMID 33019728, 2020). "FGFR1 amplification on chromosome 8p11–12 is the most common FGFR1 alteration, occurring in 14% of breast cancers and 16–27% of luminal B breast cancer, where it is associated with poor prognosis, shorter overall survival and resistance to endocrine therapies." (PMID 31987043, 2020). "The amplification of FGFR1 represents the most frequent genomic alteration in breast cancer, whereas the amplification of the FGFR2-4 genes is less common." (PMID 33081025, 2020). "Breast cancer has the seventh strongest correlation (Rho = 0.177) between average FGFR1 mRNA and average leptin mRNA among all primary cancers that showed the highest significance between FGFR1 mRNA and leptin mRNA (p = 3.17 × 10−9)." (PMID 33019728, 2020). "FGFR1 amplification was found to promote the resistance of luminal B type breast cancer to hydroxytamoxifen, whereas inhibition of FGF-signaling by siFGFR1 abrogated this resistance." (PMID 31948066, 2020). "Recently, it was demonstrated that, in ER+ breast cancer cells, the activation of the FGFR1/3-STAT3 signaling pathway leads to resistance to the PI3K/mTOR inhibitor named NVP-BEZ235." (PMID 33081025, 2020). "Both populations were highly tumorigenic – as few as 50 to 100 CD44+/CD24− and CD133+ breast cancer cells induced tumors in NOD/SCID mice – and expressed stem cell associated genes, including Oct4, Notch1, Aldh1, Fgfr1 and Sox1." (PMID 32430004, 2020).
breast cancer (continued). "Next, an adverse prognostic impact of FGFR1 expression has been assessed in the luminal A subtype of breast cancer." (PMID 33081025, 2020). "Chromosomal amplification processes involving FGFR1 were detected in 10% of breast cancers, especially in estrogen receptor positive cancers." (PMID 33352931, 2020). "These new findings, in conjunction with prior studies demonstrating that leptin drives obesity-mediated breast tumor progression, provided rationale for analyzing the relationship between FGFR1 mRNA and the leptin receptor (LepR) mRNA in breast cancer." (PMID 33019728, 2020). "In conclusion, fibroblast growth factor receptor alterations (e.g., FGFR1 copy number variations and FGFR2 SNPs) influence the risk and prognosis in patients with breast cancer." (PMID 32852708, 2020). "PD173074 is known to be a selective inhibitor of FGFR1, but can block breast cancer cell proliferation via the FGFR4 signaling pathway." (PMID 32555680, 2020). "In this regard, it has been demonstrated that ER+ breast cancer cell lines harboring the amplification of FGFR1 rely on active FGFR1 signaling for anchorage-independent cell growth and resistance to endocrine therapy." (PMID 33081025, 2020). "Knockdown of FGFR1 expression in a FGFR1-overexpressing TNBC cell line MDA-MB-231 significantly reduced cell migration and knock-out of FGFR1 reduced primary tumor growth and metastasis in a mouse mammary tumor model." (PMID 31987043, 2020). "There is a significant relationship between leptin mRNA and FGFR1 mRNA in normal breast tissue, primary breast cancer tumor tissue, and breast cancer-adjacent tissue; however, there is a difference in the directionality of the relationship." (PMID 33019728, 2020). "FGFR1 alterations have been described in several tumor types, including lung cancer, breast cancer, head and neck squamous cell cancers, and esophageal cancers 22-25." (PMID 32626515, 2020). "Both FGFR1 and LepR, independently, have been shown to increase breast tumor size and lead to a reduced overall survival in breast cancer patients." (PMID 33019728, 2020). "Another pathway has been described, using the fibroblast growth factor receptor 1 (FGFR1)-induced murine mammary carcinoma model." (PMID 32635472, 2020). "In a study on FGFR1 analyses regarding gene copy number and its relationship with clinicopathological parameters among ER-positive/HER2-negative primary breast cancer, a high level of FGFR1 expression was detected in about one-fourth of the subjects." (PMID 31754359, 2019). "A different approach to investigate the role of FGFR1 in TNBCs was a study that examined the sensitivity of a panel of 31 breast cancer cell lines to the selective FGFR inhibitor PD173074." (PMID 31754359, 2019). "FGFR1-amplified/ER+ breast cancer cells and MCF-7 cells transduced with FGFR1 were resistant to fulvestrant ± ribociclib or palbociclib." (PMID 30914635, 2019). "FGFR1 is amplified in 8.7% of all breast cancers and this was shown as an independent predictor of overall survival." (PMID 31142340, 2019). "While some of these genetic FGFR alterations were shown to predict for sensitivity to FGFR inhibitor treatment, in other studies (e.g., in lung and breast cancer) the correlation between FGFR1 amplification and FGFR inhibitor sensitivity was less clear." (PMID 31527449, 2019). "In a phase II cohort of patients with HER2-negative breast cancer with FGFR1 amplification, 8 patients received AZD4547." (PMID 35582593, 2019). "The repressive effects of FGFR1 siRNAs on ZEB1 levels were also observed in the basal-like breast cancer, Hs-578T, and MDA-MB231 cells, which expressed FGFR1(IIIc) isoform." (PMID 31682640, 2019). "HSPGs, such as syndecan-1 and syndecan-4, have been associated with breast cancer progression by the formation of complexes with FGF2 and fibroblast growth factor receptor 1 (FGFR-1)." (PMID 31013618, 2019).
breast cancer (continued). "Of note, all three ER+/HER2−/FGFR1-amplified breast cancer cell lines used herein also harbor CCND1 amplification." (PMID 30914635, 2019). "Autophagy has been previously reported in FGFR1‐amplified lung cancer models and a single breast cancer line following FGFR inhibition with AZD4547 or PD166866, respectively." (PMID 30537101, 2019). "Data concerning the clinical efficacy of a FGFR1 inhibitor used in combination with hormonal treatment in cases of breast cancer are still scarce." (PMID 31126332, 2019). "The combined use of a FGFR1 blocker and aromatase inhibitors is appealing for treating breast cancer patients with FGFR1 amplification." (PMID 31126332, 2019). "Further, CCND1 is highly overexpressed in FGFR1-amplified breast cancers and the co-amplification of these two genes correlates with poor patient outcome." (PMID 30914635, 2019). "The FGF2/FGFR1 paracrine loop is involved in the cross-talk between breast cancer cells and components of the tumor stroma as cancer-associated fibroblasts (CAFs)." (PMID 30866584, 2019). "Recently, FGFR1 activation was identified as the primary mechanism by which obesity drives estrogen receptor positive mammary tumor progression following endocrine deprivation." (PMID 31311976, 2019). "TCGA reported FGFR1 amplification and/or overexpression in 15% of ER+ breast cancers whereas in MONALEESA-2, we only detected FGFR1 amplification in ctDNA in 5% of plasma specimens." (PMID 30914635, 2019). "The combination of nintedanib (200 mg/bid) plus letrozole (2.5 mg/d) effectively inhibited both FGFR1 and aromatase in breast cancer patients, as evidenced by plasma FGF23 and 17-B-estradiol levels." (PMID 31126332, 2019). "FGFR1 is not only considered important for breast cancer tumorigenesis, but it also has been recently discovered to promote breast cancer metastasis." (PMID 30713601, 2019). "Among ER+ breast cancers, 15% harbored FGFR1 gene amplification and/or mRNA overexpression whereas 2.5, 1.9, 2.4, and 1.7% harbored amplification and/or mRNA overexpression of CRKL, HCK, FRK, and FGR, respectively." (PMID 30914635, 2019). "Further, FGFR1/2 alterations in plasma tumor DNA were detected at the time of progression on palbociclib in a small cohort of patients with advanced ER+ breast cancer." (PMID 30914635, 2019). "Here, we provided novel insights into the ability of estrogens to regulate a feedforward FGF2/FGFR1 activation between the ER-negative CAFs and breast cancer cells." (PMID 30866584, 2019). "Together, these studies suggest that the differential FGFR1 alternative splicing events play an important role in breast cancer." (PMID 30713601, 2019). "Chromogenic in situ hybridisation indicated that breast cancer patients with FGFR1 amplification in the ER-positive group were characterised by lack of PR expression and were at a significantly higher risk for development of distant metastases." (PMID 31142340, 2019). "Our findings indicate that GPER mediates a feed-forward FGF2/FGFR1 engagement within the tumor microenvironment linking CAFs to breast cancer cells toward tumor progression." (PMID 30866584, 2019). "To study the mechanism of FGFR1 signaling in human breast cancer progression, we generated DCIS-Ctrl control cell lines containing an empty vector and DCIS-iFGFR1 cell lines expressing the C-terminally HA-tagged iFGFR1 fusion protein." (PMID 30111373, 2018). "In summary, our results indicate that TNFAIP3 is essential for FGFR1 signaling-induced breast cancer cell growth in culture and tumor growth in vivo." (PMID 30111373, 2018). "FGFR1 expression has been demonstrated to play imperative roles in mammary development and breast cancer tumourigenesis." (PMID 30359238, 2018). "Anti-tumor effects were also recognized in cholangiocarcinoma harboring a FGFR2 fusion and in FGFR1 amplified breast cancer." (PMID 30181810, 2018).